SNORD26 (small nucleolar RNA, C/D box 26)
Synonyms: U26; RNU26
Gene: Small nucleolar RNA gene on chromosome 11 (62,855,292 to 62,855,366, reverse strand). Ensembl gene ENSG00000276788.
Gene Ontology:
Biological process: RNA processing
Cellular component: nucleolus
Homologues: Orthologues: chimpanzee SNORD26 (96% identical), macaque SNORD26 (95% identical), mouse Gm25894 (91% identical), rat Snord26 (87% identical), dog SNORD26 (85% identical), pig SNORD26 (85% identical), guinea pig SNORD26 (79% identical), rabbit SNORD26 (77% identical), tropical clawed frog SNORD26 (63% identical).
Diseases named in the same sentence as SNORD26 in open-access papers:
SNORD26 is named in the same sentence as 2 diseases in open-access papers, as found by Europe PMC text mining. Sharing a sentence is not in itself a finding about the gene and the disease. The quoted sentences say what the papers report.
infection (1 paper, 2022). The state of being infected such as from the introduction of a foreign agent such as serum, vaccine, antigenic substance or organism. "The silencing of SNORA/Ds encoded within RPS11 (SNORD35B), SNHG3 (SNORA73A, SNORA73B), and SNHG1 (SNORD22, SNORD25, SNORD26, SNORD27, SNORD28, SNORD29, SNORD30, SNORD31) inhibited infection with influenza A virus." (PMID 36430145, 2022).
SNORD26 also shares sentences with these, for which no sentence is quoted: osteoarthritis (1 paper).